ABO (ABO, alpha 1-3-N-acetylgalactosaminyltransferase and alpha 1-3-galactosyltransferase)
Diseases named in the same sentence as ABO in open-access papers (continued):
Sharing a sentence is not in itself a finding about the gene and the disease.
Thrombocytopenia (2 papers, 2012 to 2016). A reduction in the number of circulating thrombocytes. "The results indicate that there are genetic properties related to the maternal ABO genotype that influence the immune response that cause severe thrombocytopenia in the newborn of anti-HPA-1a immunized mothers." (PMID 22110529, 2012). "A possible correlation between the maternal ABO blood group phenotype, or underlying genotype, and severe thrombocytopenia in the newborn was investigated." (PMID 22110529, 2012). "A correlation has recently been reported between maternal ABO phenotype and ABO genotype with the severity of thrombocytopenia in the newborn; blood group O immunized women were at lower risk of having a child with severe FNAIT than blood group A women." (PMID 26564154, 2016). "The ABO distribution among immunized women was investigated, and the maternal ABO phenotype and ABO genotype was correlated to the severity of thrombocytopenia of the newborn." (PMID 22110529, 2012). "However, when it comes to development of NAIT, the different risks of severe thrombocytopenia observed in genetic subgroups of blood group A support the hypothesis that a genetic linkage may be involved, rather than the ABO phenotype itself even though the mechanism is still not understood." (PMID 22110529, 2012).
toxoplasmosis (2 papers, 2013 to 2021). A parasitic disease contracted by the ingestion or fetal transmission of toxoplasma gondii. "Studies of the association between ABO, H, Lewis, and Secretor histo-blood group carbohydrates and infection by Toxoplasma gondii and toxoplasmosis." (PMID 34222043, 2021). "Results of testing the effects of age, toxoplasmosis, RhD phenotype, ABO phenotype, and RhD-toxoplasmosis and ABO-toxoplasmosis interaction on personality traits and intelligence." (PMID 23593448, 2013). "To study the effect of interactions and several potential confounding variables we performed General Linear Model analyses with independent variables age, toxoplasmosis, RhD phenotype, ABO phenotype and RhD phenotype-toxoplasmosis and ABO phenotype-toxoplasmosis interactions." (PMID 23593448, 2013).
Abdominal obesity (1 paper, 2023). Excessive fat around the stomach and abdomen. "The study population was subsequently divided into two subgroups with and without abdominal obesity (AbO+, AbO−)." (PMID 36672616, 2023).
acute respiratory distress syndrome (1 paper, 2021). Progressive and life-threatening pulmonary distress in the absence of an underlying pulmonary condition, usually following major trauma or surgery. "In addition, a growing body of evidence suggests that transfusing larger volumes of ABO “compatible,” but non-identical plasma is associated with an increase in complications such as sepsis, acute respiratory distress syndrome (ARDS), and mortality." (PMID 34944667, 2021).
alcoholic cirrhosis of the liver (1 paper, 2022). "Some studies have shown that ABO blood grouping that varies by race may contribute to the availability of organ donors while others have shown that Blacks have a higher rate of alcoholic cirrhosis of the liver." (PMID 35936191, 2022).
ascariasis (1 paper, 2012). An infection that is caused by the roundworm Ascaris lumbricoides, many cases of which remain asymptomatic. "The results provided some evidence that pretreatment of ascariasis before vaccination improved both vibriocidal antibody levels and Th1 cytokine responses to CT-B, but in the case of vibriocidal antibody levels there was a significant interaction with ABO blood group." (PMID 22287972, 2012).
Autoimmunity (1 paper, 2011). The occurrence of an immune reaction against the organism's own cells or tissues. "Outside of the HLA region, we discovered the association of several genes with autoantibody positivity, including evidence for association of the ABO blood gene with autoimmunity and also, surprisingly, a strong association of the known autoimmunity gene, FCRL3, with IA-2A, but not with T1D." (PMID 21829393, 2011).
babesiosis (1 paper, 2023). Babesiosis refers to a condition caused by microscopic parasites that infect the red blood cells. "The analysis of state-specific data revealed limited associations between ABO antigens and Babesia infection." (PMID 36696414, 2023). "We also assessed possible associations between RhD and ABO blood types and disease severity among hospitalized babesiosis patients in Connecticut." (PMID 36696414, 2023). "In this study, we sought to determine if RhD and ABO RBC antigens are associated with B. microti infection, as determined by B. microti 18S rRNA, or babesiosis disease severity." (PMID 36696414, 2023). "Future studies should quantify the impact of RhD, ABO, and other RBC antigens on Babesia infection, and the mechanisms by which they impact RBC invasion and babesiosis severity." (PMID 36696414, 2023).
bacterial vaginosis (1 paper, 2015). Infection caused by bacterial overgrowth in the vagina. "Specifically, this study correlated mucosal ABO blood group antigen expression in saliva, vaginal and cervical secretions to the incidence of HIV, Bacterial vaginosis, Trichmonas vaginalis and Neisseria gonorrhea among female sex workers in Nairobi, Kenya." (PMID 26186209, 2015).
bone marrow failure (1 paper, 2017). "In order to identify possible risk factors for thrombosis in PNH, different risk factors like age, gender, rate of bone marrow failure, PNH granulocyte clone size, LDH level, and polymorphism of ABO gene were analyzed." (PMID 29190926, 2017).
cancer of the liver (1 paper, 2017). "A genome-wide association study has noted a direct link of single nucleotide polymorphisms at the ABO locus to serum levels of tumor necrosis factor-alpha, an inflammatory cytokine known to modulate risk of liver cancer." (PMID 28880901, 2017). "The present study noted several novel associations between ABO blood type and risk of cancer of the liver and urinary bladder." (PMID 28880901, 2017).
candidiasis (1 paper, 2022). Infection with the organism Candida. "Relating to infections, rs3131623 in HLA gene region was associated with chronic hepatitis infection (p = 5.07 × 10–7), and rs600038 in ABO gene region was associated with candidiasis (p = 2.35 × 10–5)." (PMID 36167494, 2022).
cerebrovascular disease (1 paper, 2022).
childhood asthma (1 paper, 2020). "Based on the known biological function of FUT2 for the secretion of A and B antigens on epithelial surfaces, including airway epithelium, we looked for evidence of an association between the ABO locus on chromosome 9 and childhood asthma with severe exacerbations." (PMID 33328473, 2020).
cholera (1 paper, 2011). "Thus, the ABO blood group system is a potential factor that may affect vaccination efficacy in different settings, and this factor has now been included in the assessment of ongoing cholera vaccine trials." (PMID 22216364, 2011).
cholestasis (1 paper, 2024). Impairment of the bile flow caused by obstruction within the liver, or outside the liver in the bile duct system. "Previous studies regarding cholestasis in infants with HDFN do not include ABO immunizations since it is very unlikely that it will cause this complication." (PMID 39685506, 2024).
chronic GvHD (1 paper, 2023). "While we did not observe any significant differences in ABO compatibility between the three groups, BM grafts, proven to decrease the risk of chronic GvHD, were more frequently used in the Haplo-HSCT group than in the HLA-matched groups." (PMID 37958420, 2023).
chronic kidney disease (1 paper, 2013). Impairment of the renal function secondary to chronic kidney damage persisting for three or more months. "The patient we isolated our control-IgG from suffered from chronic kidney disease that required plasma exchange to remove ABO incompatible antibodies from circulation prior to kidney transplant." (PMID 23927715, 2013).
congenital hypothyroidism (1 paper, 2013). A thyroid hormone deficiency present from birth. "Among them, the reported signals at SOX9, ABO, SASH1, GLIS3 and MIR1179 will need to be confirmed in other studies; but one of them - GLIS3- is a prime candidate, because it is involved in congenital hypothyroidism." (PMID 23408906, 2013).
dental caries (1 paper, 2025). The decay of a tooth, in which it becomes softened, discolored, and/or porous. "This cross-sectional study investigated the association between ABO blood groups and dental caries and gingivitis among a sample ofIndian adults." (PMID 41466694, 2025). "Dental caries and gingivitis are highly prevalent worldwide, with limited evidence on the role of ABO blood groups in influencingsusceptibility among Indians." (PMID 41466694, 2025).
diabetic kidney disease (1 paper, 2024). Progressive kidney disorder caused by vascular damage to the glomerular capillaries, in patients with diabetes mellitus. "We present a case report of a 51-year-old male with ESRD secondary to diabetic kidney disease who underwent desensitization for ABOi KT, involving rituximab administration followed by IA using Glycosorb® and Vitrosorb SECORIM®-ABO columns and plasmapheresis (PP)." (PMID 39006667, 2024).
diphtheria (1 paper, 2024). A Gram-positive bacterial infection caused by Corynebacterium diphtheriae. "Finally, we analyzed changes in the concentrations of other blood antibodies such as Ig, vaccine-induced antibodies (diphtheria, pneumococcus, and tetanus), and natural anti-ABO isohemagglutinins." (PMID 39534185, 2024).
Diplopia (1 paper, 2022). Diplopia is a condition in which a single object is perceived as two images, it is also known as double vision. "Nonetheless, our off-the-records analysis on non-naïve patients, who were treated with doses as high as 8 units ONA and 30 units of ABO per injection point (lateral and medial upper eyelid), was not related to ptosis or diplopia." (PMID 35622608, 2022).
ear infection (1 paper, 2017). A viral or bacterial infection that affects the external, middle, or inner ear. "Although MAGENTA pathway analysis did not identify significant pathways of interest, variants in FUT2 and ABO, which are involved in the GSL biosynthesis pathway and were implicated in our mumps GWAS, were also significantly associated with childhood ear infection." (PMID 28928442, 2017).
Erythema nodosum (1 paper, 2024). An erythematous eruption commonly associated with drug reactions or infection and characterized by inflammatory nodules that are usually tender, multiple, and bilateral. "By contrast, some risk factors, such as ABO blood group, Filipino ancestry, or lack of erythema nodosum among black individuals, are repeated in the literature despite the lack of supporting studies or biologic plausibility." (PMID 38667927, 2024).
fallopian tube cancer (1 paper, 2017). A primary or metastatic malignant neoplasm that affects the fallopian tube. "ABO blood type (N = 694) and/or ABO genetic variants (N = 154) were available for a total of 713 Tumor Registry confirmed ovarian or fallopian tube cancer cases from the VUMC." (PMID 28448592, 2017).
fetal hydrops (1 paper, 2022). "Moreover, there was no abnormal values associated with maternal red cell alloimmunization, essentially meaning Rh-alloimmunization and ABO-alloimmunization, further excluding immune fetal hydrops." (PMID 35646098, 2022).
gastroenteritis (1 paper, 2023). An inflammatory disorder that affects the upper and lower gastrointestinal tract. "Human rotaviruses attach to histo-blood group antigens glycans and null alleles of the ABO, FUT2 and FUT3 genes seem to confer diminished risk of gastroenteritis." (PMID 36970669, 2023).
gynecological cancer (1 paper, 2018). "We therefore retrospectively evaluated and compared the clinic-pathological findings including relapse-free survival (RFS), disease-specific survival (DSS), and overall survival (OS) of a large gynecological cancer patient cohort (n = 974) to the ABO BG status." (PMID 29596526, 2018).
hemochromatosis (1 paper, 2024). A disorder of iron metabolism characterized by a triad of HEMOSIDEROSIS; LIVER CIRRHOSIS; and DIABETES MELLITUS. "We also did not include variants which could be highly pleiotropic, such as the variants harboring HFE-hemochromatosis (rs1800562/rs1799945) and ABO gene region as per our previous study." (PMID 38926684, 2024).
Hepatitis (1 paper, 2024). Inflammation of the liver. "Third, the impact of ABO blood groups on PLC may be diluted or even masked by more dominant risk factors, such as hepatitis." (PMID 39911665, 2024).
hereditary elliptocytosis (1 paper, 2025). Hereditary elliptocytosis (HE) is a rare clinically and genetically heterogeneous disorder of the red cell membrane characterized by manifestations ranging from mild to severe transfusion-dependent hemolytic anemia but with the majority of patients being asymptomatic. "In this study, two DAT-negative ABO-incompatible neonates with elevated ETCOc levels were found to have other etiologies of hemolysis: G6PDd and hereditary elliptocytosis." (PMID 41007072, 2025).
idiopathic scoliosis (1 paper, 2025). A scoliosis with no known cause. "Several genetic loci, including SLC39A8 and ABO, have been established as significantly associated with adolescent idiopathic scoliosis risk in the Han Chinese population." (PMID 41211406, 2025).
IgA nephropathy (1 paper, 2026). "Elevated pre-transplant non-HLA PRA was associated with prior sensitization, IgA nephropathy, and African American ancestry, but was independent of age, ABO type, and HLA cPRA." (PMID 41816322, 2026).
infective endocarditis (1 paper, 2025). Infective endocarditis (IE) is an infection of the inner lining of the heart chambers (endocardium) and valves. "This study demonstrates that the distribution of ABO/Rh blood groups among patients with infective endocarditis differs significantly from that in the general population, with an overrepresentation of the B− type." (PMID 41303137, 2025).
iron deficiency (1 paper, 2011). "These were iron deficiency, parity, ABO phenotype and adolescence." (PMID 21345193, 2011).
kernicterus (1 paper, 2023). A term used pathologically to describe BILIRUBIN staining of the BASAL GANGLIA; BRAIN STEM; and CEREBELLUM and clinically to describe a syndrome associated with HYPERBILIRUBINEMIA. "Vasa previa, ruptured cord, twin-twin transfusion, Rhesus and ABO isoimmunization, kernicterus, etc." (PMID 36824654, 2023).
knee osteoarthritis (1 paper, 2024). "In this study, the distribution of ABO and Rh blood types in patients with knee osteoarthritis was evaluated." (PMID 38827876, 2024).
leukoplakia (1 paper, 2020). A white patch or plaque on a mucous membrane that cannot be characterized clinically or pathologically as any other disease. "But there was no significant ABO antigen loss between OSMF and leukoplakia patients (P>0.05)." (PMID 32334486, 2020).
lung adenocarcinoma (1 paper, 2022). A carcinoma that arises from the lung and is characterized by the presence of malignant glandular epithelial cells. "Further pairwise comparison showed that there were differences in ABO blood group composition between lung adenocarcinoma, lung squamous carcinoma and small cell lung cancer, and the control group, and the results were statistically significant (P < 0.01)." (PMID 36464709, 2022). "Univariate analysis showed that the ABO blood group distribution of lung adenocarcinoma, lung squamous cell carcinoma, and small cell lung cancer was different from that of the control group (P < 0.01)." (PMID 36464709, 2022).
lung disease (1 paper, 2009). "We hypothesized that genetically determined ABO histo-blood group antigen (ABH) differences in glycosylation may lead to differences in microbial binding by airway mucus, and thus predispose to early lung infection and more severe lung disease in a subset of patients with CF." (PMID 19169360, 2009).
malocclusion (1 paper, 2025). "This research aims to investigate the correlation between ABO bloodgroups and the type and severity of malocclusion based on Angle's classification in orthodontic patients." (PMID 41170032, 2025). "Therefore, it is of interest to study ABO blood group correlation with angle'sclassification and malocclusion severity in orthodontic patients." (PMID 41170032, 2025).
mastitis (1 paper, 2025). Inflammation of breast tissue during lactation or postpartum due to an obstructed duct or infection. "We show that blood group genes ABO and ACHE (Cartwright blood group) mediate regulatory effects on protein concentration and mastitis via expression and splicing, supporting conserved and widespread regulatory effects on mammalian complex traits." (PMID 40688095, 2025). "Also, gene expression and splicing of ABO (Histo-blood group) and ACHE (acetylcholinesterase, Cartwright blood group) affected protein concentration and mastitis, respectively." (PMID 40688095, 2025). "We identified many new or unannotated loci, including two blood group genes, ABO (Histo-blood group) and ACHE (acetylcholinesterase, Cartwright blood group), affected protein concentration and mastitis, respectively, via both gene expression and splicing in blood." (PMID 40688095, 2025).
metastasis (1 paper, 2014). The spread or migration of cancer cells from one part of the body (where they first appeared) to another. "SNPs associated with the CEA level and regional lymph metastasis, rs1047781 (chr19- FUT2) and rs8176746 (chr9- ABO), were not the independent contributors to disease-free survival." (PMID 24941225, 2014).
Middle East respiratory syndrome (1 paper, 2021). A viral respiratory infection that is caused by the MERS coronavirus (MERS-CoV), which most often manifests with moderate to severe respiratory symptoms, including productive cough and shortness of breath, which can progress to pneumonia and acute respiratory distress syndrome. "Previous studies have shown susceptibility of ABO blood groups to viruses such as Middle East Respiratory Syndrome (MERS), hepatitis B, human immunodeficiency virus, norawalk virus, rotavirus, dengue virus, and SARS coronavirus." (PMID 34796130, 2021).
Miscarriage (1 paper, 2022). A pregnancy that ends at a stage in which the fetus is incapable of surviving on its own, defined as the spontaneous loss of a fetus before the 22th week of pregnancy. "Potential interaction between the ABO blood group of mother/father mating and the history of spontaneous miscarriage were investigated by three models." (PMID 35602516, 2022).
monocytic leukemia (1 paper, 2023). "Associations of the ABO blood groups included monocytic leukemia, tonsilitis, renal dialysis, diseases of the female reproductive system, and osteoarthrosis." (PMID 36892462, 2023).
multiple endocrine neoplasia type 1 (1 paper, 2017). An autosomal dominant tumor predisposition syndrome caused by pathogenic variants in the MEN1 gene, characterized by an increased risk of tumors of the parathyroid glands, pituitary gland, and foregut neuroendocrine tumors (most commonly pancreatic islet cells). "However, only a few studies evaluating the role of the ABO blood type in the prevalence of NETs in multiple endocrine neoplasia type 1 (MEN1) and Von Hippel-Lindau (VHL) disease, two inherited endocrine tumor syndromes, have been published thus far." (PMID 28903383, 2017).
myeloid leukemia (1 paper, 2009). A clonal proliferation of myeloid cells and their precursors in the bone marrow, peripheral blood, and spleen. "It is surprising that no ABO LOH was observed as a substantial proportion of myeloid leukemias have deletions including the 9q34 region where ABO is located." (PMID 19274076, 2009).